MDM2 (MDM2 proto-oncogene)
Diseases named in the same sentence as MDM2 in open-access papers (continued):
Sharing a sentence is not in itself a finding about the gene and the disease.
glioblastoma (continued). "Chromothripsis occurred in 29.3% glioblastomas (36/123) and mostly affected chromosomes 7, 9 and 12, with amplification of oncogenes (EGFR, MDM2/CDK4), and homozygous deletion of tumor suppressor genes (CDKN2A)." (PMID 30542515, 2018). "These represented additional oncogene containing regions that are amplified in glioblastoma, with CDK4 being in one and MDM2 (murine double minute homolog 2) in the other." (PMID 28655341, 2017). "In our previous study, we found that miR-17-5p targeted an oncogene, MDM2 and a tumor suppressor PTEN simultaneously, resulting in chemoresistance and generation of TSCs in glioblastoma." (PMID 24912422, 2014). "Five moderate to high-level amplified genes in glioblastomas identified in this study, EGFR, PDGFRA, CDK4, MDM2 and CYP27B1, have also been previously reported, sometimes with co-amplification." (PMID 22691727, 2012). "In a survey of 456 glioblastomas, 13.4% had amplifications of CDK4 but only 9.2% had amplification of MDM2." (PMID 22691727, 2012). "Up to 10% of the most malignant astrocytic tumours, glioblastomas (WHO malignancy grade IV) show MDM2 gene amplification with consequent mRNA overexpression." (PMID 18781178, 2008). "Despite these setbacks, MDM2 inhibitors such as navtemadlin and brigimadlin continue to advance in clinical development, with multiple ongoing Phase II and III trials investigating their efficacy in malignancies, including myelofibrosis and glioblastoma." (PMID 41170373, 2025). "Other dual-therapy regimens being examined are combined inhibition of AKT/mTOR and MDM2 in glioblastoma, and combined c-MET and EGFR in non-small lung cancer." (PMID 26955870, 2016). "To examine the effect of SNP309 on MDM2 expression, we compared the levels of P2-MDM2 mRNA in glioblastomas without MDM2 gene amplification in relation to SNP309 genotype." (PMID 18781178, 2008). "In this report, we show that the mdm2 (murine double minute 2) gene induced the expression of the mdr1 gene and P-gp in human glioblastoma U87-MG cells, which did not express the MDM2 protein or P-gp." (PMID 8883415, 1996). "Our bioinformatics studies by Targetscan 7.1 and miRwalk 2.0 site have predicted that miR-548x and miR-4698 could simultaneously target 3ʹUTR of PI3KCB, PI3KCA, PDK1, AKT1, mTOR, MDM2, Rheb, and CREB1 genes that some of them were upregulated in glioblastoma sample according TCGA deta." (PMID 32005873, 2020).
glioblastoma (continued). "According to our bioinformatics studies in the TargetScan 7.1 and miRwalk 2.0 database, we predicted that some miRNAs, as well as miR-548x and miR-4698 could target some genes that are overactive in the PI3K/AKT pathway (PI3KCB, PI3KCA, PDK1, AKT1, Rheb, MDM2, mTOR, and CREB1) in glioblastoma." (PMID 32005873, 2020). "However, serum starvation was recently shown to lead to alterations in miRNA expression profiles, and miR-17 could allow glioblastoma cells to survive longer during serum starvation and could target MDM2 and PTEN with MDM2 acting as an oncogene." (PMID 26472185, 2015). "In the light of our findings, it could be of interest to analyze the patterns of Mdm2 expression and HCMV positivity in glioblastomas and establish whether strong Mdm2 expression might correlate with the absence of HCMV infection or the expression of viral proteins." (PMID 26656605, 2015). "Gene expression analysis performed using the TCGA database revealed that MDM2 and p16INK4a gene expression levels differ among patients with cancers, including those with glioblastoma multiforme; it is not known whether the regulatory regions of these genes have polymorphisms." (PMID 21637567, 2010). "Across multiple gene expression datasets including PA, adult glioblastoma (GBM), pediatric high-grade glioma (pHGG), diffuse intrinsic pontine glioma (DIPG), ependymoma (EP) and normal brain (NB) and cerebellum (CB) samples, aneuploid PA tumors demonstrated the highest levels of MDM2 expression." (PMID 26378811, 2015). "Other studies have shown that co-amplification of CDK4 and MDM2, with or without chromosome 1, gain results in worse overall survival while isolated chromosome 1 or 19 gain without CDK4/MDM2 co-amplification results in somewhat better survival in IDH-wildtype glioblastomas." (PMID 32640746, 2020).
glioma (113 papers, 1997 to 2025). A benign or malignant brain and spinal cord tumor that arises from glial cells (astrocytes, oligodendrocytes, ependymal cells). "A recent study has demonstrated that ctDNA from metastatic brain tumors, including mutations in ALK and MDM2, can be used to effectively differentiate metastatic brain tumors from gliomas." (PMID 41219968, 2025). "The results showed that inhibiting MDM2 increased the sensitivity of glioma cells to TMZ, as evidenced by a reduction in the number of viable cells in MDM2-deficient glioma cells." (PMID 37509518, 2023). "The AEG-1 and MDM2 levels increased with the advanced stages of glioma, and high AEG-1 and MDM2 levels were associated with poor overall survival." (PMID 33918653, 2021). "It is likely that MDM2-regulated cell cycle progression is associated with its function in glioma cell proliferation." (PMID 33005102, 2020). "Mdm2 and Crem are associated with glioma, leukemia, prostate cancer, chronic myeloid leukemia, and several other cancer pathways, whereas, Gsk3b is an antitumor gene associated with prostate cancer." (PMID 31523185, 2019). "MDM2 was associated with tumor initiation and development of human glioma." (PMID 28744466, 2017). "MDM2 is associated with tumor initiation and development of human glioma." (PMID 28744466, 2017). "Overall, larger, prospective studies are needed to verify whether there is a clear involvement of this or other MDM2 polymorphism(s) in glioma tumourigenesis." (PMID 18781178, 2008). "In high-risk gliomas, recurrent CNVs—such as chromosome 7/12 amplifications (EGFR, CDK4/MDM2) and chromosome 1/8/13 deletions (CHD5, DLC1, RB1)—play pivotal roles in promoting proliferation, immune evasion, and DNA repair defects." (PMID 40636690, 2025).
glioma (continued). "Another study reveals that genetic or chemical inhibition of MDM2 obviously blocked Y-box-binding protein-1-mediated temozolomide resistance in glioma cells." (PMID 37291112, 2023). "Mechanistically, PDIA3P1 promoted PMT by disrupting the C/EBPβ/MDM2 complex to inhibit the ubiquitination of C/EBPβ, enabling glioma cells to obtain stronger TMZ therapy resistance." (PMID 35836243, 2022). "Known prominent events include TMPRSS2-ERG in PCa, EGFR, CDK4, and MDM2 in glioma, and CCND1 in BrCa." (PMID 34891161, 2021). "AEG-1 and MDM2 levels correlated with poor OS and pathologic stage but did not correlate with age, gender, tumor location and diameter and Cox regression analysis identified AEG-1 and MDM2 expressions as significant prognostic factor for glioma." (PMID 33671513, 2021). "The overexpression of AEG-1 protected glioma cells from apoptosis induction following MDM2 knockdown." (PMID 33918653, 2021). "There were multiple, cancer type–specific hot spots of junctions located near known oncogenes such as KIT, PDGFRA, EGFR, CDK4, MDM2 (glioma), TMPRSS2, ERG (PCa), FGFR1, and CCDN1 (BrCa)." (PMID 34891161, 2021). "The proportion of CD8 T-cells, another prominent immune cell type in high-grade gliomas, was associated with oncogene amplifications in MYCN, PDGFRA, and MDM2." (PMID 34496929, 2021). "In this study, 47.6% of glioma patients were detected ctDNA including 1p/19q, MDM2, ERBB2, IDH1, CDKN2A, CDK4, PDGFRA, CCNE1, MET." (PMID 32973641, 2020). "we identify miR-585 as a novel dysregulated miRNA in gliomas and also an anti-proliferative regulator in glioma cells, wherein the targeted MDM2 plays a critical role." (PMID 33005102, 2020).
glioma (continued). "In this study, we report an anti-proliferative function of miR-585 in human glioma cells, where the targeted MDM2 constitutes a critical mechanism." (PMID 33005102, 2020). "Among the predicted targets, the murine double minute 2 (MDM2) is of great interest due to its important role in glioma cell proliferation." (PMID 33005102, 2020). "Among ctDNA positive glioma patients, 30% of them were detected 1p/19q codeletion and MDM2 amplification in both tissue and blood." (PMID 32973641, 2020). "We demonstrate that miR-585 inhibits glioma cell proliferation predominantly by suppressing MDM2 expression." (PMID 33005102, 2020). "Taken together, these mechanistic studies demonstrate that MDM2 is a critical target through which miR-585 inhibits glioma cell proliferation." (PMID 33005102, 2020). "These several lines of evidence demonstrate that miR-585 suppresses MDM2 expression in glioma cells through direct targeting." (PMID 33005102, 2020). "To further shed light on the contribution of regulated MDM2 to miR-585 inhibitory effect on glioma cell proliferation, we restored MDM2 expression in miR-585-overexpressing U251 cells by transient transfection." (PMID 33005102, 2020). "In accordance with this, miR-585 overexpression decreased MDM2 expression in glioma cells (upper), and reversely, its knockdown led to an increased expression of MDM2 (lower)." (PMID 33005102, 2020). "Among the selected genes, 15 (Araf, Braf, Kras, Ccnd1, Cdk6, Igf1r, Nras, Pik3ca, Pik3r1, Pdgfra, Pdgfrb, Pdgfb, Akt1, Akt2, and Mdm2) were related to glioma and leukemia." (PMID 31523185, 2019). "ENST00462717 suppresses proliferation, survival, and migration by partially regulating the MDM2/MAPK pathway in glioma." (PMID 29552296, 2018). "In contrast, the expression of the oncogenes c-myc and MDM2 increased in the irradiated shRNA-PER2 U343 glioma cells." (PMID 27036047, 2016). "Utilizing the R2 database tool, we sought to investigate MDM2 expression comparatively across PA, as well as in other gliomas and control brain samples." (PMID 26378811, 2015). "It confers glioma cell sensitivity to teniposide through binding to the 3’-UTR region of MDM2 leading to its reduced expression." (PMID 25151861, 2014). "To determine if miR-181b-enhanced glioma cell sensitivity to teniposide was directly mediated by MDM2, we transfected glioma cells with miR-181b alone or together with mutant MDM2." (PMID 25151861, 2014). "Microarray from our group also showed that MDM2 is one of the 85 downregulated genes in glioma cells with stable overexpression of miR-181b." (PMID 25151861, 2014). "More importantly, we demonstrated that miR-181b promotes the sensitivity of glioma cells to teniposide through direct modulation of the level of MDM2." (PMID 25151861, 2014).